GSDMB (gasdermin B)
Diseases named in the same sentence as GSDMB in open-access papers (continued):
Sharing a sentence is not in itself a finding about the gene and the disease.
tumor (continued). "Similarly, CD8+ T cells and NK cells were recently shown to trigger tumor clearance through the GSDMB-granzyme A axis, and this process is enhanced by IFN-γ." (PMID 32778143, 2020). "Thus, GSDMB amplification was detected in 21 tumours, and 15 of them (71.4%) were HER2-positive cases, therefore confirming the association between the both amplifications (p = 0.034)." (PMID 27462779, 2016). "First, the analysis of a series of 28 HER2-positive tumours in the discovery series, treated with the neoadjuvant setting revealed an association between GSDMB amplification and the lack of pathologic complete response (pCR) (p = 0.001)." (PMID 27462779, 2016). "Therefore, GSDMB is functionally involved in promoting aggressive tumour behaviour and reduced clinical response to anti-HER2 therapies." (PMID 27462779, 2016). "Overall, previous literature proposed that GSDMA is considered a tumor suppressor gene according to its pro-apoptotic effect in cancer cells, while GSDMB gene, which is up-regulated in some cancer types, might have a tumor-promoting role." (PMID 24675552, 2014). "While both GSDMB isoforms promote cell motility and invasion through activation of the Rho-GTPases Rac-1 and Cdc-42 in vitro, their analysis in xenograft mouse models showed that only GSDMB-2 increases tumor growth and metastasis." (PMID 24675552, 2014). "Similarly, inactive isoforms that avoid immune‐mediated cell death may result from tumor‐specific splicing of genes like GSDMB." (PMID 41399527, 2025). "Therefore, therapies that selectively produce cytotoxic GSDMB isoforms through alternative splicing may improve anti-tumor immunity." (PMID 40452932, 2025). "Importantly, tumor cells often co‐express various cytotoxic and noncytotoxic GSDMB variants simultaneously." (PMID 40783818, 2025). "In addition to tumor cells, we found that some immune cells also expressed GSDMB." (PMID 38711020, 2024). "For example, gasdermin B (GSDMB) was reported to be highly expressed in digestive system epithelial cell-derived tumor cells, and the induction of pyroptosis by GSDMB could enhance antitumor immunity 22, suggesting a potential strategy for anticancer therapy by inducing pyroptosis in tumor cells." (PMID 38250606, 2024). "Thus, exogenous GSDMB may potentially act as a tumor suppressor by activating pyroptosis to achieve antitumor immunity." (PMID 37454146, 2023). "Interestingly, when we treated tumor cells with IFNγ, GSDMB was also increased in tumor cells." (PMID 37587833, 2023). "Furthermore, CD8 + T and NK cells were demonstrated to trigger tumor clearance through the GSDMB-granzyme A axis, which could be enhanced by IFN-γ." (PMID 37635159, 2023). "Therefore, it has been suggested that GSDMB may act as an oncogene to facilitate this process during tumor progression and metastasis." (PMID 35321945, 2022). "Therefore, to expand GSDMB potential as therapy target, in the present work, we aimed at identifying other druggable pathways, controlling GSDMB pro-tumor functions, that could be readily translated into the clinic." (PMID 36163066, 2022). "Additionally, it has been demonstrated that NK and CD8+ T cells can induce pyroptosis in cancer cells that express GSDMB to promote tumor clearance via the GzmA-GSDMB axis, moreover, this process is enhanced by interferon-γ (IFN-γ) and tumor necrosis factor (TNF)." (PMID 36523974, 2022). "However, GSDMB is overexpressed in several kinds of cancers and has also been proposed to exert pro-tumor activities, though how this protein promotes tumor progression remains unclear." (PMID 33406603, 2021). "Upon tumor-selective activation in metastatic bone niches, this nanotherapy induces STING-driven immune priming and GSDMB-mediated pyroptosis, triggering potent antitumor responses." (PMID 41576171, 2026). "Despite both GSDME and GSDMB being triggered by killer cells, GSDME appears to have stronger tumor-suppressive properties." (PMID 41291696, 2025).
tumor (continued). "GSDMA, GSDMB, GSDMD, and GSDME displayed significantly higher expression in tumor stage 2 and 3 than in normal tissues." (PMID 39607202, 2024). "The expression levels of GSDMB and GSDME were higher in tumor grades 2 and 3 compared to normal tissues, whereas GSDMA expression level was significantly increased in tumor grade 2 compared to normal tissues." (PMID 39607202, 2024). "Our previous study discovered that the gasdermin family members are involved in the occurrence and development of HCC, the expression of GSDMB and GSDMD is significantly higher in HCC tumor samples compared with corresponding normal samples." (PMID 37061535, 2023). "Earlier study has already demonstrated that granzyme A can cleave and activate GSDMB, a member of gasdermin protein family in a NLRP3‐dependent manner, then induce tumor cell pyroptosis and mediate tumor immunotherapy." (PMID 37817895, 2023). "Considering the literature and our experimental results suggesting that the caspase-1/GSDMB axis plays an important role in triggering pyroptosis, we analyzed the expression profiles of the GSDMB and caspase-1 genes in LUAD tumor tissues in the GEPIA database." (PMID 37705753, 2023). "GSDMB has a positive protective effect on the prognosis of BLCA (p < 0.0001) and SKCM (p = 0.00729) tumor patients in BLCA tumors with a prognosis of approximately 6 years." (PMID 37064151, 2023). "Tumor CD8+ cells (representing CD8+ T cells) and CD57+ cells (representing NK cells) downregulated pyroptosis expression percentage, especially GZMA+ and GSDMB+, acting as a protective prognostic predictor clinically." (PMID 37620327, 2023). "It was found that after GSDMB knockdown, IBI315‐induced pyroptotic‐like tumor cells decreased significantly." (PMID 37587833, 2023). "Previous reports have shown that when GZMA cleaved GSDMB or GZMB cleaved GSDME, NK cells and CD8(+) T cells directly triggered pyroptosis of tumor cells." (PMID 37221570, 2023). "Aside from caspases, granzyme A has been reported to cleave GSDMB in lymphocytes, and granzyme B was reported to directly cleave GSDME in tumor cells, ultimately contributing to tumor suppression by invoking pyroptosis." (PMID 36093182, 2022). "IHC staining validated that the protein levels of AIM2, CASP4, GSDMB, NOD2, and RBCK1 in tumor tissues were much higher than that in adjacent normal tissues." (PMID 36248876, 2022). "Gasdermin B (GSDMB) and Gasdermin E (GSDME) are cleaved by Granzymes A and B, respectively, into their active pore-forming subunits inducing death of tumour cells by pyroptosis and resulting in local inflammation." (PMID 35626754, 2022). "Then, we investigated the expression levels of AIM2, CASP4, GSDMB, NOD2, and RBCK1 in cell lines and tumor tissues by qRT-PCR, IHC." (PMID 36248876, 2022). "Latest studies reported that two other members of the GSDM family, GSDMB and GSDME, are cleaved by granzymes of killer lymphocytes to potentiate anti-tumor immunity via induction of tumor-cell pyroptosis." (PMID 36323669, 2022). "Latest studies reported that GSDMB and GSDME in tumor cells are proteolyzed by granzymes of killer lymphocytes to trigger pyroptosis." (PMID 36323669, 2022). "QRT-PCR showed that the expression of AIM2, CASP4, GSDMB, NOD2, and RBCK1 was significantly upregulated in tumor samples." (PMID 36248876, 2022). "Therefore, GSDMB function may affect tumor progression and metastasis." (PMID 35954405, 2022). "Results confirmed that GSDMA was substantially overexpressed in eight cancers tissues compared to normal tissues, whereas GSDMB and PJVK had a high inter-tumor heterogeneity between paracancerous and tumor tissues." (PMID 35922531, 2022). "In other investigations, GSDMA, GSDMB, GSDMC, and GSDMD have also been shown to have tumor-suppressing properties." (PMID 35769504, 2022).
tumor (continued). "Based on the analysis of UALCAN, the expression of all GSDM family members was increased in tumor-stage 1–3 subgroups, and the expression of GSDMA, GSDMB, GSDMC, and PJVK was higher in all four tumor-stage subgroups than in normal subgroups." (PMID 36505798, 2022). "Once cleaved, GSDMB and GSMDE induce the death of tumor cells by pyroptosis, resulting in low-grade local inflammation that is essential for successful clearance of tumors by myeloid cells." (PMID 33868312, 2021). "Activated GSDMB and GSDME induce the pyroptosis of cancer cells and enhance anti-tumor immunity, thus creating a positive feedback loop of pyroptosis and anti-tumor immunity." (PMID 34931767, 2021). "Thus, GSDMB may play a role in tumor progression and metastasis." (PMID 34858408, 2021). "Furthermore, GSDMB could promote tumor progression and metastasis in mouse xenograft models." (PMID 33634141, 2021). "For instance, a research report showed that granzyme A (GrA) could cleave gasdermin B (GSDMB, one of members in gasdermin family) to induce pyroptosis, thereby enhancing anti-tumor immunity." (PMID 40761801, 2025). "For several cancer subtypes, pyroptosis promotes tumor growth and metastasis through inflammatory cytokine release, activation of oncogenic signaling pathways (e.g., STAT3, PI3K), and dysregulation of gasdermin proteins (e.g., GSDMB, GSDMC)." (PMID 40200299, 2025). "The DEGs included genes involved in cell proliferation and migration (e.g., COL11A1), tumor‐promoting factors that degrade the extracellular matrix (e.g., MMP11), as well as immunosuppressive (TGFB1) and proinflammatory responses (TNFRSF6B, IFNGR2, GSDMB)." (PMID 40952312, 2025). "Activated cytotoxic lymphocytes release IFN-γ, which upregulates GSDMB expression, thereby promoting pyroptosis in esophageal carcinoma cell lines (OE19 and OE33) and a breast cancer cell line, thereby enhancing the tumor cell pyroptosis induced by T cells." (PMID 38987821, 2024). "GSDMB can be induced by interferon gamma (IFN-γ) and tumor necrosis factor alpha (TNF-α), which could be released by tumor-infiltrating CD8 T cells and other immune cells, thus providing a positive feedback loop." (PMID 36742298, 2023). "The increase in GSDMB could strengthen cell pyroptosis and antitumor effects induced by IBI315, forming a positive feedback to achieve the maximum killing of tumor cells." (PMID 37587833, 2023). "The tumor cells pyroptosis is triggered by NK cells and CD8+ T cells through granzyme‐A/GSDMB axis." (PMID 37125240, 2023). "We expect that this LNP formulation can be delivered into tumor tissue where the mRNA is translated into the N-terminal domain of GSDMB protein, triggering pyroptosis directly without protease cleavage." (PMID 37454146, 2023). "Third, although GSDMB localization is usually diffuse cytoplasmic or nuclear, a concurrent dotted staining was observed for GSDMB, Rab7 and LC3B puncta within tumor cells." (PMID 36163066, 2022). "Notably, the expression levels of 5 PRGs (CASP1, CASP3, CASP6, GSDMB, and GZMA) were lower in both CRC tissues and the high-stage group, suggesting that their potential function as tumor suppressors in CRC tumorigenesis and development." (PMID 35937993, 2022). "Only upon immune activation, mouse immunocytes released GZMA that cleaved human GSDMB, thus indicating that triggering an endogenous tumor reduction in vivo via GSDMB-mediated pyroptosis is not spontaneous and requires additional signals." (PMID 35281099, 2022). "At the same time, the heatmap showed that AIM2, GSDMB and GSDMC were overexpressed in tumor group." (PMID 36034461, 2022). "Furthermore, AIM2, CASP4, GSDMB, NOD2, and RBCK1 were also found to be highly expressed in ccRCC cell lines and tumor tissues, and GASP4 and GSDMB promote ccRCC cells’ proliferation, migration, and invasion." (PMID 36248876, 2022). "Once cleaved, GSDMB and GSDME induce pyroptosis in tumor cells." (PMID 36159393, 2022).
tumor (continued). "In conclusion, GSDMD, GSDMB, and AIM2 are all promising new targets in cancer therapy, which may be involved in the death mechanism of tumor cell therapy through pyroptosis." (PMID 36569221, 2022). "Respectively, they engrafted CT26 cells and B16-F10 cells with recombinant human GSDMB into mice subcutaneously, and found that GZMA/GSDMB pathway-mediated pyroptosis strengthened tumor clearance in the mouse model by enhancing the therapeutic efficacy of antitumor immunity." (PMID 35847844, 2022). "Because GSDMB were preferentially expressed by tumor cells of MIBC, targeted induction of tumor cell pyroptosis could be theoretically achieved." (PMID 35479097, 2022). "The results revealed significantly reduced tumor volume and mass and even no tumor after knocking down GSDMB, which was consistent with the results of the in vitro experiments." (PMID 34326684, 2021). "GSDMA, GSDMC and PJVK are not detected in most human tissues (both tumor tissues and normal tissues), while GSDMB, GSDMD and GSDME are highly expressed in most human tissues (both tumor tissues and normal tissues), especially GSDMD." (PMID 34421915, 2021). "For example, gasdermin B (GSMDB) and gasdermin E (GSDME) are cleaved into their membrane pore-forming fragments by the enzymes granzyme A and B, respectively, when granzymes are delivered directly into the tumor cell during the attack by cytotoxic T cells." (PMID 33868312, 2021). "Importantly, this alteration was observed only in tumours that also presented ERBB2 amplification (58/67; 86%); thus, none of the 459 HER2-negative cases was identified as harbouring GSDMB amplification." (PMID 27462779, 2016). "Among the 37 non-responder tumours, 31 (83.8%) showed GSDMB gene amplification and 33 (89.2%) protein expression." (PMID 27462779, 2016). "Furthermore, GZMA can induce pyroptosis, an immune-related cell death process, by cleaving Gasdermin B (GSDMB) protein in tumor cells, which may help limit tumor progression." (PMID 39228516, 2024). "Moreover, GSDMB expression in tumors significantly increases the efficacy of immune checkpoint blockade (ICB), suggesting pyroptosis can synergize with ICB to promote anti-tumor immunity." (PMID 36742298, 2023). "When T cells were cultured in the condition media of GSDMB knocked down in tumor cells, T cells could no longer be activated." (PMID 37587833, 2023). "Furthermore, human GSDMB expresses PD-L1 in mouse colon cancer and melanoma cells without affecting tumor growth in immunocompetent mice." (PMID 37705746, 2023). "Interestingly, the robust pyroptosis induction observed in vitro seems not to directly affect tumor development in vivo, as GSDME deficiency or GSDMB overexpression failed to alter tumor growth." (PMID 36077828, 2022). "Therefore, consistent with the pro-cancer effect of GSDMB in human HER2-positive carcinomas, the results in murine models show that GSDMB2 promotes tumor incidence specifically in the context of HER2/NEU-driven carcinogenesis." (PMID 35281099, 2022). "Specifically, Granzyme A released from cytotoxic lymphocytes cleaves Gasdermin B (GSDMB) to trigger pyroptosis in target tumor cells, while cytotoxic lymphocytes secreted Granzyme B or chemotherapy-induced activated caspase 3 cleaves Gasdermin E (GSDME) to trigger tumor pyroptosis." (PMID 36280674, 2022). "In this study, we found that the pyroptosis genes including GSDMB, GSDME, NLRC4, NLRP2 and GZMA were hazardous genes in AML, and the genes of proinflammatory cytokines such as IL6 and TNF were found to be protective genes which maybe related with tumor microenvironment." (PMID 36553549, 2022). "However, whether GSDMB has inherent oncogenic, or tumor suppressor function in vivo has not been demonstrated yet in preclinical mouse models, since mice lack GSDMB orthologue." (PMID 35281099, 2022). "Additionally, the prognosis value of GSDMB in these datasets was not independent of tumor grade." (PMID 27462779, 2016).
tumor (continued). "However, the implication of GSDMB in carcinogenesis and tumor progression is not well understood." (PMID 24675552, 2014). "However, the results revealed that BRQ treatment did not activate GSDMA, GSDMB, or GSDMC in tumor cells." (PMID 41144149, 2025). "Moreover, in animal experiments, we observed that N87 cells were no longer sensitive to IBI315 following GSDMB knockdown and had decreased infiltration of CD3+ and CD8+ lymphocytes in the tumor." (PMID 37587833, 2023).